APIP (APAF1 interacting protein)
Description:
Catalyzes the dehydration of methylthioribulose-1-phosphate (MTRu-1-P) into 2,3-diketo-5-methylthiopentyl-1-phosphate (DK-MTP-1-P). Functions in the methionine salvage pathway, which plays a key role in cancer, apoptosis, microbial proliferation and inflammation. May inhibit the CASP1-related inflammatory response (pyroptosis), the CASP9-dependent apoptotic pathway and the cytochrome c-dependent and APAF1-mediated cell death.
Synonyms: hAPIP; CGI-29; Mmrp19; APIP2; CGI29
Tractability: PROTAC: ubiquitination databases record sites on it; its protein half-life has been measured.
Gene: Protein-coding gene on chromosome 11 (34,853,094 to 34,916,520, reverse strand). Ensembl gene ENSG00000149089.
Subcellular location: Cytoplasm
Subcellular location (Human Protein Atlas): Nucleoplasm; Cytosol
Pathways (Reactome):
Programmed Cell Death: Formation of apoptosome; Regulation of the apoptosome activity
Metabolism: Methionine salvage pathway
Gene Ontology:
Molecular function: identical protein binding; methylthioribulose 1-phosphate dehydratase activity; protein binding; zinc ion binding; metal ion binding
Biological process: negative regulation of apoptotic process; protein homotetramerization; pyroptotic inflammatory response; S-adenosylmethionine cycle; regulation of ERK1 and ERK2 cascade
Cellular component: cytoplasm; cytosol
Genetic constraint (gnomAD): Loss-of-function variants: 25 observed, 24.52 expected, observed/expected ratio (o/e) 1.02, 90% interval 0.74 to 1.42. The upper end of that interval is the gene's LOEUF score, 1.42, which puts it in group 5 of 6, group 1 being the genes least tolerant of losing a copy. Missense variants: 218 observed, 249.73 expected, observed/expected ratio (o/e) 0.87, 90% interval 0.78 to 0.98. Synonymous variants: 85 observed, 77.18 expected, observed/expected ratio (o/e) 1.1, 90% interval 0.92 to 1.32.
Homologues: Orthologues: chimpanzee APIP (100% identical), macaque APIP (99% identical), rabbit APIP (95% identical), mouse Apip (94% identical), guinea pig APIP (93% identical), pig APIP (93% identical), rat Apip (92% identical), tropical clawed frog apip (80% identical), zebrafish apip (77% identical), Drosophila melanogaster CG11134 (62% identical), dog APIP (62% identical), Caenorhabditis elegans ZC373.5 (38% identical).
Diseases named in the same sentence as APIP in open-access papers:
APIP is named in the same sentence as 31 diseases in open-access papers, as found by Europe PMC text mining. Sharing a sentence is not in itself a finding about the gene and the disease. The quoted sentences say what the papers report.
lung disease (4 papers, 2012 to 2020). "Although EHF and APIP are the nearest genes to the intergenic chr11 GWAS locus with significant lung disease association p-values, PDHX is best predicted to be regulated by SNPs in the region based on current gene expression data." (PMID 33253230, 2020). "The fifth locus, on chr11p12-p13 (EHF/APIP; P=1.9 × 10−10), was previously shown to be associated with lung disease." (PMID 26417704, 2015). "Genetic variants located in the 3′ UTR region of APIP were found to be associated with lung disease severity in cystic fibrosis." (PMID 23285211, 2012).
non-small cell lung carcinoma (4 papers, 2012 to 2022). A group of at least three distinct histological types of lung cancer, including non-small cell squamous cell carcinoma, adenocarcinoma, and large cell carcinoma. "Inversely, APIP was found to be down-regulated at mRNA and protein levels in non-small cell lung carcinoma cells and tumors." (PMID 23285211, 2012). "Similarly, mRNA and protein expressions of APIP were reported downregulated in non-small cell lung carcinoma." (PMID 36529823, 2022). "Finally, APIP is altered in non-small cell lung carcinoma (NSCLC) tumor." (PMID 26942872, 2016).
gastric cancer (3 papers, 2013 to 2025). A primary or metastatic malignant neoplasm involving the stomach. "In the present study, we report an important function of APIP in ERBB2/ERBB3 signaling in gastric cancer." (PMID 26942872, 2016). "Our findings provide APIP with an oncogenic function which had previously been suggested by reports showing increased expression or gene amplification of APIP in a variety of human cancers (early and advanced), including gastric cancer." (PMID 26942872, 2016). "We also evaluated APIP mRNA and protein levels in a panel of human gastric cancer cell lines (SNU-1, -5, -16, -216, -484, -601, -620, -638, -668 and -719)." (PMID 26942872, 2016). "Western blot analysis revealed an increased expression of APIP in 29 (26.4%) samples out of all gastric cancer tissues." (PMID 26942872, 2016). "To characterize the role of APIP in gastric tumorigenesis, we examined APIP expression in human gastric cancer tissues." (PMID 26942872, 2016). "To explore how APIP regulates AKT and ERK1/2 signaling in gastric cancer cells, we employed a pull-down assay using 3xFLAG-tagged APIP followed by a liquid chromatography-tandem mass spectrometry (LC-MS/MS) analysis." (PMID 26942872, 2016). "In SNU-16 gastric cancer cells, APIP knockdown decreased the phosphorylation of AKT (Ser473 and Thr308) and ERK1/2." (PMID 26942872, 2016). "Cell proliferation was significantly enhanced by APIP overexpression in SNU-620 gastric cancer cells (SNU-620/APIP)." (PMID 26942872, 2016). "In gastric cancer, APIP also forms a tetrameric complex and the inhibition of APIP/APIP interactions blocks its oncogenic activity." (PMID 26942872, 2016). "The increased expression of APIP in gastric cancer cells enhances the HRG-β1/ERBB3-induced activation of AKT and ERK1/2 which stimulate cell proliferation and positively increase tumorigenesis by elevating ELK-1, C-FOS or cyclin D1." (PMID 26942872, 2016). "On the contrary, APIP knockdown suppressed the proliferation in SNU-16 gastric cancer cells (SNU-16/shAPIP #2 and #3)." (PMID 26942872, 2016). "Most human gastric cancer cell lines expressed APIP but highly metastatic SNU-16 cells showed the highest expression of them all." (PMID 26942872, 2016). "APIP (located in chromosome region 11p13) amplification has also been observed in gastric cancer cell lines and gastric cancers." (PMID 26942872, 2016). "APIP levels are frequently increased in human gastric cancers and gastric cancer-derived cells." (PMID 26942872, 2016). "Therefore, APIP can serve as a potential therapeutic target in gastric cancer, specifically targeting ERBB3 signaling in APIP-overexpressing cancers." (PMID 26942872, 2016). "We then assessed whether APIP expression influences growth characteristics of gastric cancer cells." (PMID 26942872, 2016). "Overall, these results suggest that APIP stimulates cell proliferation via ERBB3, acting in conjunction with ERBB2, in gastric cancer cells." (PMID 26942872, 2016). "We show that in addition to CD44/SLC1A2 in gastric cancer, SLC1A2 is involved in a novel but analogous gene fusion, APIP/SLC1A2, in colon cancer." (PMID 23637631, 2013). "Our findings offer compelling evidence that APIP plays an essential role in ERBB3 signaling as a positive regulator for tumorigenesis, warranting future development of therapeutic strategies for ERBB3-driven gastric cancer." (PMID 26942872, 2016). "In summary, this is the first report showing that APIP displays a pivotal oncogenic activity by binding to ERBB3 to stimulate the formation of ERBB3/ERBB2 heterodimer, leading to amplification of HRG-mediated signaling involved in cell proliferation and tumorigenesis in gastric cancer." (PMID 26942872, 2016).
breast carcinoma (2 papers, 2013 to 2023). "Other regions included RIMS2, known to be associated with particularly aggressive breast cancers, and APIP, which binds HER3 receptor, leading to the heterodimerisation between HER2 and HER3 and resulting in sustained activation of downstream signalling." (PMID 36661191, 2023).
colon cancer (1 paper, 2013). "By paired-end RNA sequencing (RNA-seq) of SNU-C1 cells, we uncovered a novel colon cancer gene fusion, APIP/SLC1A2." (PMID 23637631, 2013).
diabetes (1 paper, 2025). "This is particularly intriguing, as APIP was found to be redox modulated in the diabetes model presented here, hinting at a potential interplay between phosphorylation and oxidation in regulating the protein’s function." (PMID 40319072, 2025).
endotoxemia (1 paper, 2025). "APIP and GGCT were identified in the perfused heart dataset and found to be thiol redox modulated in hearts from mice subjected to endotoxemia or the STZ Type I diabetes model." (PMID 40319072, 2025).
gastric adenocarcinoma (1 paper, 2016). "When we further assessed the clinicopathological and prognostic roles of APIP expression in human gastric tissues using immunohistochemistry (IHC), we observed a strong staining of APIP in gastric adenocarcinoma specimens, compared to normal samples (data not shown)." (PMID 26942872, 2016).
heart failure (1 paper, 2019). Inability of the heart to pump blood at an adequate rate to meet tissue metabolic requirements. "The increase in APIP expression in the cardiomyocytes under hypoxia and in human patients with heart failure led us to investigate the role of APIP in MI." (PMID 31263105, 2019). "Given that the increased expression of APIP regulates ADORA2B level and protects the heart from MI, the increase of APIP as well as ADORA2B in the hearts of patients with heart failure is likely associated with signaling of cardioprotection during heart failure." (PMID 31263105, 2019). "Apaf-1-interacting protein (APIP) and ADORA2B transcript levels in human hearts are substantially higher in patients with heart failure than in controls." (PMID 31263105, 2019). "Interestingly, we observed similar expression patterns of APIP and ADORA2B in the hearts of patients with heart failure and of APIPTg/+ and APIP+/− mice." (PMID 31263105, 2019).
lung carcinoma (1 paper, 2015). "However, many “hits” in this study with no readily apparent representation in the lung cancer methylome-related literature were found, [e.g., PR: DARS, CLDN18, APIP; GB: ARHGEF12 PRKCE], and are likely worthy of pursuit." (PMID 26683690, 2015).
myocardial infarction (1 paper, 2019). Gross necrosis of the myocardium, as a result of interruption of the blood supply to the area, as in coronary thrombosis. "Collectively, APIP is crucial for cardioprotection against myocardial infarction by virtue of binding to and stabilizing ADORA2B, thereby dampening ischemic heart injury." (PMID 31263105, 2019). "Moreover, Adora2b D296G knock-in mice were more vulnerable than control mice to myocardial infarction and intentional increases in APIP levels overcame the defective protection of the ADORA2B SNP against ischemic injury." (PMID 31263105, 2019).
Salmonella Infections (1 paper, 2012). Infections with bacteria of the genus SALMONELLA. "Finally, using a genome wide association study, a common SNP (rs514182) associated with reduced expression of APIP has been shown to be linked to increased susceptibility to both pyroptosis caused by Salmonella infection and to the chemotherapeutic agent carboplatin." (PMID 23285211, 2012).
squamous carcinoma (1 paper, 2012). "For example, APIP was found to be amplified and up-regulated in squamous carcinoma cells lines from tongue and larynx." (PMID 23285211, 2012).
systemic inflammatory response syndrome (1 paper, 2021). SIRS is a serious condition related to systemic inflammation, organ dysfunction, and organ failure. "Reducing APIP expression could help treat systemic inflammatory response syndrome, a whole-body inflammatory state that can occur in response to infection." (PMID 35036173, 2021).
cancer (6 papers, 2012 to 2022). A tumor composed of atypical neoplastic, often pleomorphic cells that invade other tissues. "APIP has been proven to inhibit two types of programmed cell death, including apoptosis and pyroptosis, and was also found to be related to cancers and inflammatory diseases." (PMID 36196256, 2022). "Together, these results confirm the involvement of APIP in the methionine salvage pathway, which plays a key role in many biological functions like cancer, apoptosis, microbial proliferation and inflammation." (PMID 23285211, 2012). "CTSG, NLRP9, DFNB59, APIP, SCAF11, CASP5 and NAIP showed significant downregulation across cancers." (PMID 36605187, 2022). "However, APIP is discriminated from other ERBB3-binding partners, such as c-Src and p85 subunit of PI3K which also bind to the C-terminal regulatory (CR) domain of ERBB3, enabling its phosphorylation and activation in cancer cells." (PMID 26942872, 2016).
tumor (6 papers, 2016 to 2024). "The investigation of the common 68 proteins in The Human Protein Atlas database (; proteinatlas.org) revealed a similar association between tumor and normal tissues at the protein level for CKAP2L, AURKB, CDC25A, APIP, and LGALS3." (PMID 36529823, 2022). "Cell proliferation and tumor formation are repressed by APIP downregulation and stimulated by its overexpression." (PMID 26942872, 2016). "Therefore, the function of APIP in stimulating cell proliferation potentially operates in many cell types, including tumor cells and normal cells." (PMID 26942872, 2016). "Furthermore, xenograft assays in nude mice revealed a dramatic increase in tumor growth for APIP-overexpressing SNU-620 cells compared with control cells." (PMID 26942872, 2016). "This patient's tumor demonstrated 8 mutations overall including alterations in the PI3K, MAPK pathways (mutations in FBXW7, FGFR1) with concurrent epigenetic and transcriptional deregulation, specifically ARID1A, ETV1 rearrangement, NOTCH1 APIP-NOTCH1 fusion, and MYST3 amplification." (PMID 28781987, 2017).
infection (3 papers, 2012 to 2025). The state of being infected such as from the introduction of a foreign agent such as serum, vaccine, antigenic substance or organism. "To confirm that intracellular methionine levels were indeed affected by APIP knockdown, we performed HeLa cells infection experiments with either a wild type (wt) strain or a methionine auxotroph mutant (Shigella metA) of Shigella flexneri." (PMID 23285211, 2012).
heart disease (1 paper, 2023). "A study on heart disease showed that APIP was correlated with ADORA2B mRNA levels." (PMID 37938149, 2023).
APIP also shares sentences with these, for which no sentence is quoted: anaplastic astrocytoma (1 paper); angiosarcoma (1); congestive heart failure (1); cystic fibrosis (1); dilated cardiomyopathy (1); gastric tumor (1); ischemic heart disease (1); Jaundice (1); melanoma (1); pancreatic cancer (1); small cell lung carcinoma (1); T-cell acute lymphoblastic leukemia (1); Type I diabetes (1).